TNF (tumor necrosis factor)
Diseases named in the same sentence as TNF in open-access papers (continued):
Sharing a sentence is not in itself a finding about the gene and the disease.
Insulin resistance (continued). "In addition, studies have shown that IL-10 produced by Treg cells in VAT not only inhibits the release of TNF-α-induced inflammatory cytokines and chemokines but also protects adipocytes from the effects of TNF-α-induced insulin resistance." (PMID 34515616, 2021). "However, chitosan supplementation decreased plasma tumor necrosis factor (TNF)-α, insulin levels, alanine aminotransferase (ALT) activity, insulin resistance (HOMA-IR), and adipose tissue lipoprotein lipase activity." (PMID 34443619, 2021). "Studies reported that the absence of TNF-α improved insulin sensitivity in obese mice, and plasma IL-1 is an important inflammatory marker of systemic insulin resistance." (PMID 34262422, 2021). "Cordyceps may play a crucial role in the treatment of DN by targeting TNF, MAPK1, EGFR, ACE, and CASP3 signaling and involved in the inflammatory response, apoptosis, oxidative stress, and insulin resistance." (PMID 33628839, 2021). "Based on experimental studies, up-regulation of TNF-α and IL-6 induces insulin resistance through activation of JNK and MAPK signaling pathways and consequently disrupts insulin signaling pathway leading to insulin resistance." (PMID 34077450, 2021). "In separate wells, along with the differentiation cocktail, several methods to induce insulin resistance were undertaken including: 10% high serum (HS), 100 nM and 200 nM hyperinsulinemia (HI100, HI200), 1 μM dexamethasone (Dex), 2.5 nM TNFα, and a combination of hyperinsulinemia and TNFα." (PMID 33498179, 2021). "An additional factor is inflammation, suggesting that the insulin resistance characterizing T2DM may produce a large number of cytokines, including tumor necrosis factor α (TNF-α), interleukin (IL)-6, and IL-1β." (PMID 34671273, 2021). "Additionally, we examined the relationship between miRNA levels and plasma concentrations of inflammatory factors including tumor necrosis factor alpha (TNF-α) and interleukin 6 (Il-6) as well as insulin resistance." (PMID 34077450, 2021). "The production of TNF-alpha, IL-6, and CRP from adipose tissue influences insulin resistance." (PMID 34403431, 2021). "(TNF), interleukins (IL-6) and monocyte chemoattractant proteins (MCP-1) which may also accelerate the development of peripheral insulin resistance and altered glucose homeostasis." (PMID 34900829, 2021). "After 12 months of TRE, body mass was reduced by 3.4% and inflammatory markers (IL-6, IL-1β, and TNF-α), lipid profile (HDL, LDL, TG), and insulin resistance (fasting glucose, insulin, HOMA-IR) significantly improved compared with ND without affecting muscle performance." (PMID 34649266, 2021). "Furthermore, the SAM levels in plasma were related to higher fasting insulin levels, homeostasis model assessment of insulin resistance (HOMA-IR) and tumor necrosis factor-α (TNF-α) in a cross-sectional study involving 118 individuals with metabolic syndrome." (PMID 33572965, 2021). "This combination of increases in intestinal permeability and plasma LPS levels induce the production of pro-inflammatory cytokines (ILs, TNF-α) and CRP that can in turn induce the serine phosphorylation of insulin receptor substrate-1, leading to insulin resistance." (PMID 34692563, 2021). "In humans and laboratory mice with insulin resistance and T2DM, there is a lower concentration of iHsp70 and a higher concentration of eHsp70, both changes lead to an increase in TNF-α, and the higher the ratio in favor of eHsp70 the more pronounced the insulin resistance." (PMID 35050141, 2021). "In addition, adipose tissue produces adipocytokines, including leptin, adiponectin, tumor necrosis factor-α (TNF-α), that are possibly contributing to insulin resistance." (PMID 33803995, 2021). "GAL-3BP is significantly positively associated with inflammatory markers, including IL6, IL-1β, together with TNFα, and these may participate in MetS pathogenesis related to GAL-3BP, since inflammation may probably result in insulin resistance." (PMID 34858323, 2021).
Insulin resistance (continued). "TNF-α is an important pro-inflammatory mediator that contributes to decreased expression of glucose transporter 4 (GLUT4) in adipose, skeletal, and cardiac muscle tissues leading to insulin resistance and T2DM pathogenesis." (PMID 34039404, 2021). "It is well-established that hepatocyte-derived cytokines and/or chemokines, such as tumor necrosis factor-alpha (TNF-α), interleukins (ILs) and macrophage chemoattractant proteins, are involved in the onset and progression of insulin resistance and fatty liver." (PMID 34966805, 2021). "Possible mechanisms of pathogenesis of NAFLD induced by H. pylori include (i) insulin resistance; (ii) inflammatory cytokines or adipokines, particularly CRP, TNF‐α, and IL‐6; (iii) altered lipid profile; and (iv) altered intestinal permeability and gut microbiota." (PMID 33490615, 2021). "Moreover, there are lots of mediators of insulin resistance that participate in driving renal function decline, including TGF-β1, blood pressure, inflammation, TNF-α, IL-6, and oxidative stress." (PMID 33628839, 2021). "It has been speculated that inflammatory markers such as tumor necrosis factor-alpha (TNF-α), interleukin (IL) 6, and C-reactive protein (CRP) impact on endothelium dysfunction and insulin resistance and contribute to the pathogenesis of GDM." (PMID 33918528, 2021). "LKB1 interference did not affect the improvement of DHM on TNFα-induced insulin resistance, as shown by the glucose uptake assay." (PMID 34650665, 2021). "The disease is associated to a pro-inflammatory state with a moderate excess in the production of cytokines such as IL-6, IL-1 or tumor necrosis factor (TNF), which hinder the interaction of insulin with its receptor and contribute to insulin resistance and diabetes." (PMID 33578998, 2021). "However, sVNS abolished the beneficial effect of exercise on glucose intolerance and insulin resistance, decreased acetylcholine level, ChAT activity, and PKC activity, and increase TNF-α level of the spleen in HFD-mice exercise intervention." (PMID 34717724, 2021). "In rodents, obese mice lacking either TNF-α or its receptor show protection against the development of insulin resistance." (PMID 33800490, 2021). "The roles of IL-6, TNF- α, CRP, and IGF-1 in insulin resistance have been widely studied." (PMID 33432036, 2021). "Bariatric surgery is associated with decreases in CRP and interleukin-6 concentrations in proportion to weight less, however, TNF-alpha levels did not change Despite this, insulin resistance was not normalized and some adipose pathology remained post-surgery." (PMID 34760952, 2021). "Moreover, TNF-α with more lipolytic and less liposynthetic activities, induces an increase in circulating free fatty acids (FFA), which in turn leads to insulin resistance." (PMID 34078385, 2021). "Furthermore, we investigated the correlation between NGAL and tumor necrosis factor-α (TNF-α), which has been proposed as a significant predictor of insulin resistance, affecting the insulin receptor signal transduction pathways." (PMID 32377189, 2020). "Insulin resistance was induced in nondiabetic adipocytes and myocytes by either TNF exposure or treatment with high glucose and high insulin; lamivudine prevented insulin resistance induced in both these models." (PMID 32968070, 2020). "In patients with T2DM, the level of TNF-α correlated positively with HbA1c (r = 0.361, p=0.003) and HOMA-IR (r = 0.296, p=0.017), indicating a significant relationship with glycemic control and insulin resistance." (PMID 32089876, 2020). "Reactive oxygen species act as a second messenger that activates nuclear factor kappa B (NF-κB), necrosis factor-α (TNF-α), and interleukins (ILs) which reduces the expression of GLUT 4 and activates intracellular adhesion molecule-1 to stimulate the growth of insulin resistance." (PMID 33082833, 2020). "However, QSHPK1 HFD mice showed a decreased serum TNFα levels and ATM infiltration, as well as less severe insulin resistance." (PMID 33208918, 2020).
Insulin resistance (continued). "The improvement of insulin-dependent glucose uptake in such conditions indicates that TNF-α is an important mediator of insulin resistance through negative influence of this cytokine on important sites of the insulin signaling pathway." (PMID 33322719, 2020). "It is well-known that the overproduction of proinflammatory cytokines TNFα, IL-1β, IL-6, and MCP-1 might play a critical role in the development of insulin resistance and chronic inflammation in obese animals." (PMID 33297496, 2020). "It induces insulin resistance, which thus explained the negative correlation between TNFα and body fat and SSAT found in our study." (PMID 31912874, 2020). "Lutein protects against hepatic lipid accumulation and insulin resistance and attenuates lipid peroxidation by decreasing MDA (malondialdehyde) and the production of proinflammatory cytokines such as tumor necrosis factor-alpha (TNF-α) in the liver of guinea pigs." (PMID 33114278, 2020). "TNFα can activate JNKs and inhibit IRS-1 phosphorylation, leading to insulin resistance." (PMID 32878255, 2020). "The infiltration of inflammatory cells into adipose tissues leads to the increased secretion of proinflammatory cytokines and chemokines such as TNFα, MCP-1, C reactive protein (CRP), and interleukins, and these same inflammatory mediators have been shown to be upregulated in insulin resistance." (PMID 32971975, 2020). "Increases in IL-6 and TNF-α were also observed, particularly in the PCOS insulin resistance group." (PMID 32187268, 2020). "Interestingly, these white AT (WAT) CD8+ T cells produce tumor necrosis factor α (TNF-α) and interferon γ (IFN-γ), which exacerbate insulin resistance (IR)." (PMID 32973799, 2020). "TNF-α is a proinflammatory cytokine, which is involved in GDM and insulin resistance." (PMID 32377189, 2020). "TNF-α and IL-6 can alter insulin sensitivity and stimulate the phosphorylation of serine residues instead of tyrosine in insulin receptor substrate-1 (IRS-1), thus inhibiting the activation of insulin signaling and sustaining insulin resistance." (PMID 32947869, 2020). "Our results confirm previous findings on PML regulation modulated by TNFα, and may suggest a role of PML in insulin resistance." (PMID 33257747, 2020). "The impact of H. pylori infection on other organs could be mediated by increased levels of inflammatory markers such as IL-6 and tumor necrosis factor-α (TNF-α), all of which are also involved in the development of insulin resistance and T2DM." (PMID 33013895, 2020). "Independent of leptin level, serum level of TNF-α in diabetic patients correlates with the level of insulin resistance and the glucose metabolism parameters such as HbA1c." (PMID 32089876, 2020). "In this regard, some studies have suggested that increased TNF-α concentrations may impair the translocation of GLUT4 receptors, while IL-6 may have pro-inflammatory properties that lead to insulin resistance." (PMID 32187268, 2020). "Although, IL-1, TNF-α, MIF, and IL-6 have consistently been shown to cause insulin resistance in WAT, their effects have not been extensively explored in BAT at the molecular level." (PMID 32265845, 2020). "Despite clinical data demonstrating the contribution of TNF-α to the development of insulin resistance, its role is still not fully explained." (PMID 32375231, 2020). "In particular, TNF-α, IL-6, and IL-1β interfere with insulin signaling through the activation of MAPK and nuclear factor kappa-light-chain-enhancer of activated B cells (NFkB), resulting in insulin resistance." (PMID 30621146, 2019). "IL-6 and TNF activate the Janus kinase/signal transducer and activator of transcription (JAK/SAT) and mitogen-activated protein kinase (MAPK), respectively, inducing cellular damage and insulin resistance." (PMID 31878222, 2019).
Insulin resistance (continued). "Particularly, proinflammatory cytokines, such as tumor necrosis factor (TNF)-α and interleukin (IL)-6, produced and secreted from visceral adipose tissue induce insulin resistance, promote oxidative stress, and play a major role in the pathogenesis of endothelial dysfunction and atherosclerosis." (PMID 29476238, 2019). "From our results, the expression of TNFα and CCL2 was increased in adipocytes and TNFα and CCL2 could act as adipokines contributing to worsening insulin resistance in the IH condition." (PMID 31013606, 2019). "JQJT tablets could also reduce the levels of TNF-α, IL-6, and MCP-1, which were related to insulin resistance." (PMID 30733971, 2019). "In addition, in the TNF-α-induced insulin resistant cell model, we also found naringenin restored TNF-α-induced insulin resistance." (PMID 31591391, 2019). "When excessive energy is ingested, WAT stores energy in the form of triglycerides in unilocular white adipocytes, and it secretes many adipokines such as tumor necrosis factor-α (TNF-α), interleukin-6 (IL-6), and plasminogen activator inhibitor-1 (PAI-1), which induce insulin resistance." (PMID 31346340, 2019). "In summary, our results show that high glucose administration results in glucose intolerance with insulin resistance through impairment of GLP-1 secretion, elevated level of blood glucose, activation of TLR4 and subsequently increased levels of IL-6 and TNF-α in mice." (PMID 31138952, 2019). "Since treatment with IMD was demonstrated in this study to promote the expression of adiponectin and reduce the expression of TNF-α, it follows that IMD may also have an impact on insulin resistance." (PMID 31731774, 2019). "Thus, short-term exposure to high concentrations (10 ng/mL) of TNFα can induce irreversible GM1 expression, probably resulting in chronic insulin resistance." (PMID 31013778, 2019). "Unexpectedly, however, neither palmitate nor TNF‐α, which we have previously shown to evoke insulin resistance, or oleate‐induced hypertrophy significantly modified NECC2 content in 3T3‐L1 cells." (PMID 30160359, 2018). "Moreover, improved insulin resistance via inhibition of TNF-α and TNF-α-mediated inflammation by RES treatment were observed in 3T3-L1 adipocytes (Zhang, Du & Meng, 2013) and in primary human adipocytes." (PMID 29967759, 2018). "TNF-α participates in the pathogenesis of insulin resistance and is elevated in both obese and nonobese PCOS women." (PMID 30595838, 2018). "BLEx failed to induce phosphorylation of AMPK as well as did not prevent the restoration of 2-NBDG uptake under TNF-α–induced insulin resistance." (PMID 29872751, 2018). "Some studies have shown that the administration of tumor necrosis factor (TNF)-α inhibitors (TNFi), such as infliximab (IFX), etanercept (ETN) and adalimumab (ADA) improves insulin resistance in patients with rheumatic disease, while others have reported contradictory findings." (PMID 29694426, 2018). "Similarly, in the present study, bovine α-LAH not only exhibits protective effects against HFD induced insulin resistance, but also significantly downregulated inflammation-related gene (MCP-1, TNF-α and IL-6) expression in epididymal adipose tissues." (PMID 29473848, 2018). "The adiponectin/TNF-α ratio showed negative correlations with insulin resistance (r=-0.68, p<0.001) and triglyceride (r=-0.39, p=0.014) and a positive correlation with insulin sensitivity (r=0.69, p<0.001)." (PMID 29387323, 2018). "TNF-α induces serine phosphorylation in insulin receptor substrate-1 (IRS-1), resulting in the inhibition of tyrosine kinase activity in the insulin receptor and leading to insulin resistance and hyperinsulinemia." (PMID 30134857, 2018). "The implication of the TNF system in the development of insulin resistance and other metabolic consequences in non-obese, non-diabetic individuals remains to be elucidated." (PMID 29425212, 2018).
Insulin resistance (continued). "Insulin resistance (HOMA-IR), serum adiponectin, and tumor necrosis factor (TNF) were determined." (PMID 29425212, 2018). "The significant increase in the proinflamatory cytokines TNF-α, IL-6, RBP4, and progranulin, has contributed to promoting insulin resistance and triggering the inflammatory response, resulting in activation of HSCs to produce collagen and stimulate liver fibrosis." (PMID 30096951, 2018). "Furthermore, TNF-alpha has regulatory functions on adiponectin in the human visceral white adipose tissue, and TNF-alpha levels are elevated in states of insulin resistance." (PMID 28830524, 2017). "Furthermore, melatonin attenuates the secretion of pro inflammatory cytokines such as interleukin-6 (IL-6), tumor necrosis factor (TNF)-α, interferon (IFN)-gamma under insulin resistance condition in high fat diet mouse." (PMID 28764741, 2017). "In this study, CRP, IL-6, and TNF-α were significantly elevated in obese Egyptian type 2 diabetics and positively correlated with insulin resistance, non-HDL and triglycerides, key components of metabolic syndrome." (PMID 29099041, 2017). "Previous studies have been conducted on many candidate genes for PCOS, principally related to reproductive hormones, insulin resistance, and chronic inflammation, including follicle-stimulating hormone receptor (FSHR), insulin receptor (INSR), and tumor necrosis factor (TNF)." (PMID 29232372, 2017). "Furthermore, anti‐TNF‐α treatment significantly improved the insulin resistance, and anti‐RAGE significantly improved both glucose tolerance and insulin resistance compared to the control group." (PMID 28344834, 2017). "In addition, TNF-α can promote the secretion of MCP-1, which further induces the secretion of many proinflammatory cytokines that can aggravate insulin resistance through various mechanisms." (PMID 28928791, 2017). "EC also inhibited tumor necrosis factor (TNF)α-mediated altered transcription of protein tyrosine phosphatase 1B (PTP1B), leading both effects to an attenuation of the TNFα-mediated triggering of signaling cascades involved in insulin resistance." (PMID 29088075, 2017). "High levels of inflammatory mediators, such as tumor necrosis factor alpha (TNF-α), interleukin 6 (IL-6), and C-reactive protein (CRP), might contribute to an increase in insulin resistance." (PMID 28403353, 2017). "MiR-16 has been reported to play a key role in regulation of insulin signaling through a reduction in TNFα and suppressor of cytokine signaling 3 (SOCS3) signaling and increase in insulin-like growth factor binding protein-3 (IGFBP-3) levels to inhibit insulin resistance." (PMID 29214180, 2017). "Fasting blood samples were collected for assessment of nonesterified fatty acids, tumor necrosis factor-α (TNF-α), interleukin-6 (IL-6), adiponectin, insulin and estimation of insulin resistance (HOMA-IR)." (PMID 28977210, 2017). "Greater TNFα and CRP levels in the CM group could contribute to the study findings because both TNFα and CRP have been indicated to promote insulin resistance." (PMID 28713332, 2017). "An animal study showed that BBR reduced blood TNF-α, IL-6, and MCP-1 levels of JNK and IKKβ phosphorylation in obese mice fed with a high-fat diet, as well as indicated that BBR improves insulin resistance possibly through inhibiting the activation of macrophages in adipose tissue." (PMID 29164155, 2017). "TNF-α via its own receptor and via activated nuclear factor kappa-light-chain-enhancer of activated B cells (NF-kB (induces serine phosphorylation of insulin receptor substrate type 1 (IRS1), Destructive insulin resistance." (PMID 29387832, 2017). "In addition, recent studies have demonstrated that blood inflammatory cytokine TNF-α is involved in hepatic JNK activity and/or insulin resistance." (PMID 28708100, 2017).